HLA-DOA (major histocompatibility complex, class II, DO alpha)
Description:
Important modulator in the HLA class II restricted antigen presentation pathway by interaction with the HLA-DM molecule in B-cells. Modifies peptide exchange activity of HLA-DM.
Synonyms: HLA-DNA; HLA-DZA; HLA-D0-alpha; HLADZ
Tractability: Antibody: its Gene Ontology location is reachable by antibodies, with high confidence; UniProt places it where antibodies can reach, with medium confidence; UniProt predicts a signal peptide or a membrane-spanning region.
Gene: Protein-coding gene on chromosome 6 (33,004,178 to 33,009,594, reverse strand). Ensembl gene ENSG00000204252.
Subcellular location: Endosome membrane; Lysosome membrane
Pathways (Reactome):
Immune System: MHC class II antigen presentation
Gene Ontology:
Molecular function: MHC class II protein complex binding; protein binding; MHC class II receptor activity; peptide antigen binding
Biological process: negative regulation of antigen processing and presentation of peptide antigen via MHC class II; antigen processing and presentation of exogenous peptide antigen via MHC class II; peptide antigen assembly with MHC class II protein complex; positive regulation of immune response; positive regulation of T cell activation; antigen processing and presentation; immune response
Cellular component: MHC class II protein complex; late endosome membrane; lysosomal membrane; plasma membrane; endosome membrane; membrane
Genetic constraint (gnomAD): Loss-of-function variants: 28 observed, 23.31 expected, observed/expected ratio (o/e) 1.2, 90% interval 0.89 to 1.64. The upper end of that interval is the gene's LOEUF score, 1.64, which puts it in group 6 of 6, group 1 being the genes least tolerant of losing a copy. Missense variants: 324 observed, 335.54 expected, observed/expected ratio (o/e) 0.97, 90% interval 0.88 to 1.06. Synonymous variants: 137 observed, 141.48 expected, observed/expected ratio (o/e) 0.97, 90% interval 0.84 to 1.12.
Homologues: Orthologues: chimpanzee HLA-DOA (99% identical), dog HLA-DOA (80% identical), macaque MAMU-DOA (80% identical), pig SLA-DOA (79% identical), mouse H2-Oa (73% identical), rat RT1-DOa (71% identical), guinea pig HLA-DOA (66% identical). Paralogues in human: HLA-DQA1 (56% identical), HLA-DPA1 (55% identical), HLA-DQA2 (55% identical), HLA-DRA (54% identical), HLA-DMA (26% identical), HLA-DPB1 (24% identical), HLA-DQB1 (23% identical), HLA-DQB2 (23% identical), HLA-DRB1 (23% identical), HLA-DRB5 (22% identical), HLA-DOB (20% identical), HLA-DMB (20% identical), and 1 more.
Diseases named in the same sentence as HLA-DOA in open-access papers:
HLA-DOA is named in the same sentence as 43 diseases in open-access papers, as found by Europe PMC text mining. Sharing a sentence is not in itself a finding about the gene and the disease. The quoted sentences say what the papers report.
asthma (3 papers, 2017 to 2022). "In severe cases of asthma, epithelial gene expression of HLA-DOA has been shown to be significantly reduced in the central airways." (PMID 32245788, 2020). "Notably, HLA-DOA, a hypermethylated/low-expression gene, was only one gene that enriched in the pathway of asthma." (PMID 36550577, 2022). "In the previous study, HLA-DOA genes were found a remarkable association with increased risk of diisocyanate-induced asthma, which revealed the closely correlation between HLA-DOA and asthma and provided a promising direction of the pathogenesis of asthma." (PMID 36550577, 2022). "For example, HLA-DRA, HLA-DOA, and HLA-DQA1 are all components of pathways that play a role in hypothyroidism, RA, asthma, and antigen processing and presentation." (PMID 32245788, 2020). "Moreover, Chemokine (C-C Motif) Ligand 5 (CCL5) was significantly reduced within the central airways in severe asthma, as was the epithelial gene expression for the MHC class II, DO alpha (HLA-DOA), which regulates peptide loading and is involved in antigen presentation." (PMID 28045928, 2017).
breast carcinoma (3 papers, 2013 to 2021). "Breast cancer tissue of celecoxib-treated patients showed a significantly increased expression of MHC class II genes, including HLA-DRα and HLA-DRβ2, CD74 (MHC class II invariant chain) and HLA-DM, but not HLA-DQ and HLA-DOA." (PMID 23566419, 2013).
periodontitis (3 papers, 2020 to 2023). An acute or chronic inflammatory process that affects the tissues that surround and support the teeth. "Additionally, LRPPRC may potentially impact the MHC molecules HLA-B and HLA-DOA in periodontitis." (PMID 37892851, 2023). "Interestingly, both IGF2R and HLA-DOA have never been investigated in periodontal medicine, though these potential interactions mainly in the lysocytic/endocytic pathways should be investigated in regard to the interplay between PD and periodontitis." (PMID 33238395, 2020).
rheumatoid arthritis (3 papers, 2020 to 2024). A chronic, systemic autoimmune disorder characterized by inflammation in the synovial membranes and articular surfaces. "Yukinori Okada41 reported that HLA‐DOA was an independent risk of anticitrullinated protein autoantibody‐positive rheumatoid arthritis." (PMID 31856409, 2020).
Type-1 diabetes (3 papers, 2013 to 2020). "Recently, HLA-DOA has been implicated in other disease association studies such as type 1 diabetes and chronic lymphocytic leukemia survival, and interestingly, the same rs9296068 SNP was reported in a multistage MHC association mapping study of pediatric liver transplant rejection." (PMID 23991122, 2013).
gastric cancer (2 papers, 2019 to 2023). A primary or metastatic malignant neoplasm involving the stomach. "Furthermore, we found a correlation between high-risk gastric cancer and extracellular matrix (ECM) receptor interaction, high infiltration of macrophages, CD44, and HLA-DOA." (PMID 36968601, 2023).
colon adenocarcinoma (1 paper, 2024). "Moreover, among 19 Hub-MHCsig, HLA-DMA, HLA-DMB, and HLA-DOA were positively correlated with microsatellite instability in colon adenocarcinoma, while TAP2, TAP1, and HLA-F were negatively correlated with microsatellite instability in testicular germ cell tumors." (PMID 38714579, 2024).
retinoblastoma (1 paper, 2025). A malignant tumor that originates in the nuclear layer of the retina. "Moreover, in the high-ICI subgroup, CD83, HLA-DOA, IRF4, DOK3, and CXCR1 genes were also hypermethylated and thus associated with the presence of retinoblastoma." (PMID 41150792, 2025).
viral infections (1 paper, 2025). "BAY-M2d induced multiple antiviral genes (TLR7, CD74, CES1, HLA-DOA, CD209, and CMPL2), the products of which may be involved in resistance to viral infections." (PMID 40129989, 2025).
tumor (15 papers, 2016 to 2025). "HLA-C, which belongs to HLA-I and can present endogenous tumor antigens to kill tumor cells effectively, was less expressed in the high-risk group, while HLA-II, such as HLA-DPB2, HLA-DQB2, HLA-DOA, and HLA-DQA2, showed an increase in the high-risk group." (PMID 35754846, 2022). "Human MHC class II molecules (HLA-DMB, HLA-DMA, HLA-DRA, HLA-DOA) in the top 30 DMRs, which could attract inflammatory tumour-specific CD4+ T cells and dampen CD8+ T cell antitumour reactivity, were found to be hypomethylated in all CLL patients in our study." (PMID 36712882, 2022). "Interestingly, our study showed strong association of five HLA genes (including HLA-DMA, HLA-DMB, HLA-DOA, HLA-DRB6 and HLA-E) with delayed tumor recurrence in both cohorts." (PMID 34834481, 2021). "Additionally, ENHO was positively co-expressed with MHC class II presentation genes (including HLA-DMA, HLA-DOA, HLA-DPA1, HLA-DPB1, and HLA-DRB1), supporting its role in promoting anti-tumor immunity." (PMID 40647442, 2025). "In tumoural cases, an intense cytoplasmic and luminal secretion staining for HLA-DOA was observed in SAC neoplastic glands whereas weak cytoplasmic expression considered as negative was observed in hmMSI-H tumour cells." (PMID 30413173, 2018).
cancer (11 papers, 2015 to 2025). A tumor composed of atypical neoplastic, often pleomorphic cells that invade other tissues. "The NPS was significantly and positively associated with HLA genes, including TAP1, HLA-E, HLA-DRA, B2M, TAP2, HLA-DPA1, and HLA-DOA in all cancers." (PMID 36170029, 2022). "Thus, maintaining a functional HLA-DOA protein might form part of the immune escape strategy of cancer cells." (PMID 29855388, 2018). "In most of the cancers, there was a significant correlation between UBE2C gene expression and HLA‐DMB, HLA‐DOA, HLA‐DPA1, HLA‐PDB1, HLA‐DRA, and HLA‐E." (PMID 38577722, 2024). "Similarly, HLA-DOA regulates the level of B cell infiltration in tissue and ensures the stable expression of MHC in cancer tissue, balancing their biological functions." (PMID 36245844, 2022).
infection (4 papers, 2013 to 2025). The state of being infected such as from the introduction of a foreign agent such as serum, vaccine, antigenic substance or organism. "Some other infection-responsive genes like IFI144, MX1, MX2, IFIT3, and HLA-DOA were also observed proximal to those altered ERVs, and showed positive co-expressions with their proximal ERVs, wherever they located." (PMID 40176799, 2025). "Interestingly, at the later stages of our infection model, genes essential for correct antigen presentation (CD83, CD40, HLA-DOA) were downregulated exclusively in STM-D23580-infected cells relative to bystander cells." (PMID 30451854, 2018).
immune dysfunction (1 paper, 2012). "Together with the decline in CD4+ T cell numbers, the downregulation of TLR8, IL-8 and HLA-DOA expressed on macrophages/dendritic cells and B cells, respectively, suggests generalized immune dysfunction that can in due course lead to immune exhaustion." (PMID 22511950, 2012).
infectious disease (1 paper, 2013). A disorder directly resulting from the presence and activity of a microbial, viral, or parasitic agent in humans. "Genes regulated at 4 hours included CXCR5, HLA-DQB1, HLA-DOA, and were associated with the “antigen presentation, cellular compromise, infectious disease, respiratory disease” network (network score 46)." (PMID 23544148, 2013).
neurological disorders (1 paper, 2022). "Interestingly, several genes encoded in the HLA locus, which has been implicated in SCZ and other psychiatric and neurological disorders, were picked up by our inference downstream of the identified transcription factors (HLA-DOA, HLA-DOB, HLA-DRB1, HLA-DMA, and BRD2)." (PMID 36344995, 2022).
HLA-DOA also shares sentences with these, for which no sentence is quoted: autoimmune disease (2 papers); autoimmune thyroid disease (2); diabetes (2); systemic lupus erythematosus (2); amyotrophic lateral sclerosis (1); Autoimmunity (1); Behçet’s disease (1); cervical cancer (1); cervix tumors (1); chronic lymphocytic leukemia (1); COVID-19 (1); emphysema (1); Ewing sarcoma (1); fetal growth restriction (1); germ cell tumor (1); graft versus host disease (1); hypothyroidism (1); leukemia (1); liver cancer (1); mastitis (1); medulloblastoma (1); melanoma (1); metastatic melanoma (1); multiple sclerosis (1); osteosarcoma (1); primary Sjøgren’s syndrome (1); respiratory disease (1); serous ovarian cancer (1).